SH2D1B (SH2 domain containing 1B)
Description:
Cytoplasmic adapter regulating receptors of the signaling lymphocytic activation molecule (SLAM) family such as CD84, SLAMF1, LY9 and CD244. In SLAM signaling seems to cooperate with SH2D1A/SAP. Plays a role in regulation of effector functions of natural killer (NK) cells by controlling signal transduction through CD244/2B4 without effecting its tyrosine phosphorylation; downstream signaling involves PLCG1 and ERK activation. Activation of SLAMF7-mediated NK cell function does not effect receptor tyrosine phosphorylation but distal signaling (By similarity). In the context of NK cell-mediated cytotoxicity does not enhance conjugate formation with target cells but stimulates polarization of the microtubule-organizing center and cytotoxic granules toward the NK cell synapse. Negatively regulates CD40-induced cytokine production in dendritic cells downstream of SLAM family receptors probably by inducing activation of the PI3K pathway to inhibit p38 MAPK and JNK activation (By similarity).
Synonyms: EAT2
Tractability: PROTAC: its protein half-life has been measured.
Gene: Protein-coding gene on chromosome 1 (162,395,268 to 162,412,138, reverse strand). Ensembl gene ENSG00000198574.
Pathways (Reactome):
Immune System: Immunoregulatory interactions between a Lymphoid and a non-Lymphoid cell
Gene Ontology:
Molecular function: protein binding; protein-macromolecule adaptor activity
Biological process: leukocyte activation involved in immune response; positive regulation of innate immune response; positive regulation of natural killer cell mediated immunity
Cellular component: cytosol
Genetic constraint (gnomAD): Loss-of-function variants: 12 observed, 16.44 expected, observed/expected ratio (o/e) 0.73, 90% interval 0.47 to 1.18. The upper end of that interval is the gene's LOEUF score, 1.18, which puts it in group 5 of 6, group 1 being the genes least tolerant of losing a copy. Missense variants: 123 observed, 160.93 expected, observed/expected ratio (o/e) 0.76, 90% interval 0.66 to 0.89. Synonymous variants: 55 observed, 59.34 expected, observed/expected ratio (o/e) 0.93, 90% interval 0.75 to 1.16.
Homologues: Orthologues: chimpanzee SH2D1B (99% identical), macaque SH2D1B (97% identical), dog SH2D1B (71% identical), mouse Sh2d1b2 (66% identical), mouse Sh2d1b1 (65% identical), rat Sh2d1b2 (64% identical), zebrafish inppl1b (24% identical), Caenorhabditis elegans unc-26 (20% identical), Drosophila melanogaster Synj (16% identical), Drosophila melanogaster sp3 (14% identical), Drosophila melanogaster CG9784 (13% identical), Drosophila melanogaster CG6805 (11% identical), and 1 more. Paralogues in human: SH2D1A (36% identical), INPP5B (27% identical), INPP5D (27% identical), INPP5F (26% identical), INPPL1 (26% identical), SYNJ1 (25% identical), OCRL (23% identical), SYNJ2 (23% identical), INPP5E (19% identical), INPP5J (19% identical), SACM1L (18% identical), INPP5K (17% identical), and 1 more.
Diseases named in the same sentence as SH2D1B in open-access papers:
SH2D1B is named in the same sentence as 22 diseases in open-access papers, as found by Europe PMC text mining. Sharing a sentence is not in itself a finding about the gene and the disease. The quoted sentences say what the papers report.
depression (2 papers, 2024). "Heart failure comorbid with depression may be associated with five hub genes, including Stat4, Cd83, Cx3cr1, Col1a2, and Sh2d1b." (PMID 39295096, 2024).
colorectal cancer (1 paper, 2025). A primary or metastatic malignant neoplasm that affects the colon or rectum. "This study identified and validated a reproducible five-gene panel—DLG5, CD177, SH2D1B, NQO2, and KRT73—derived from whole-blood RNA, with strong diagnostic relevance for colorectal cancer (CRC)." (PMID 41373777, 2025).
HCMV) infection (1 paper, 2022). "This NK2 subpopulation featured high expression of NKG2C KLRC2) and low expression of PLZF (PLZF), FcεRγ (FCER1G), EAT-2 (SH2D1B), and SYK (SYK), which are used as markers for memory NK cells in the context of human cytomegalovirus (HCMV) infection." (PMID 35501841, 2022).
neuroblastoma (1 paper, 2022). Neuroblastoma (NB) is the most common solid, extracranial childhood tumor. "Our results show that high-level co-expression of SLAMF7 and SH2D1B is significantly associated with better outcome of high-risk neuroblastoma patients." (PMID 35525858, 2022). "High-level co-expression of SLAMF7 and SH2D1B was significantly associated with better survival of the high-risk neuroblastoma patients." (PMID 35525858, 2022). "Moreover, high-level co-expression of SLAMF7 and SH2D1B was significantly associated with better survival of high-risk neuroblastoma patients." (PMID 35525858, 2022).
tumor (3 papers, 2021 to 2024). "We found that numerous NK cell effector function-related genes, such as TBX21, FYN, NCR1, SH2D1A, SH2D1B, PTPN6, and IL18RAP, were downregulated in tumor-infiltrating NK cells." (PMID 34535671, 2021).
SH2D1B also shares sentences with these, for which no sentence is quoted: myeloma (3 papers); heart failure (2); infection (2); acute leukemia (1); bipolar disorder (1); cancer (1); colitis (1); COVID-19 (1); developmental delay (1); diabetes (1); malaria (1); memory impairment (1); myotonic dystrophies (1); Salmonella Infections (1); sarcoma (1); schizophrenia (1); X-linked lymphoproliferative disease (1).